JAK2 (Janus kinase 2)
Diseases named in the same sentence as JAK2 in open-access papers (continued):
Sharing a sentence is not in itself a finding about the gene and the disease.
tumor (continued). "Similarly, we identify mutations in both tumor-suppressor genes, e.g., ABL1, JAK2, MAP2K1, and KIT, from poor responders in CML, suggesting that these are two of the key mechanisms by which tumor cells evolve to acquire drug resistance." (PMID 38459554, 2024). "However, persistent activation of the JAK2/STAT3 pathway has been associated with immune ICI resistance and tumor progression." (PMID 38974233, 2024). "Importantly, gp130, a common signaling receptor subunit of the IL-6 family, was strongly correlated with JAK2 in tumor tissues (r = 0.755, P < 0.001), while a moderate correlation was observed in normal tissues (r = 0.447, P = 0.012)." (PMID 38881895, 2024). "In SA region, the expression of IL-6, gp130, and JAK2 was lower in tumor tissues in IL-6+gp130+, IL-6+JAK2+, and IL-6+gp130+JAK2+ cells (P < 0.05); and the expression of IL-6R, CRP was also lower in tumor tissues in IL-6R+CRP+, IL-6R+STAT3+, and IL-6R+CRP+STAT3+cells (P < 0.05)." (PMID 38881895, 2024). "In ESCC, advanced analyses integrating single-cell transcriptomic sequencing with bulk microarray data have uncovered that CCL18, released by TAMs, drives tumor cell proliferation via the JAK2/STAT3 signaling pathway, correlating with a poorer prognosis in ESCC." (PMID 39286635, 2024). "We also investigated the effects of RSJ on the Jak2/Stat3 signaling pathway in tumor tissue." (PMID 39203920, 2024). "In animal models, simultaneous inhibition of PI3K/mTOR and JAK2 reduces tumor growth." (PMID 38200372, 2024). "Similarly, IL-8 has been shown to promote EMT of HCC tumour cells via the JAK2/STAT3/Snail signalling pathway, and hence induce their migration and invasion." (PMID 37894344, 2023). "Similarly, JAK2 staining was present within the tumour cell cytoplasm and stromal areas of some patients as shown in representative images." (PMID 37199043, 2023). "JAK2/STAT3 pathway can regulate tumor occurrence and development." (PMID 36814203, 2023). "Similarly, in xenograft mice transplanted with HepG2 cells, treatment with etomidate, an inhibitor of JAK2, led to the inhibition of tumor growth and subsequent increases in animal survival." (PMID 37762066, 2023). "However, surprisingly, the concurrent findings of a JAK2 V617F mutation raised more challenging questions and included in the differential diagnosis PMF or a hybrid MDS/MPN neoplasm that was unclassifiable." (PMID 36810551, 2023). "In addition to this, the expression level of JAK2 is correlated with multiple human cancers, with its downregulation in tumor cells relative to normal tissue cells." (PMID 37873786, 2023). "In addition, inhibition of janus kinase 2 (JAK2)/STAT3 was found to reduce MDSCs in the tumor ecosystem through the inhibition of VEGFA and casein kinase 2 (CK2) in HNSCC transgenic mouse models." (PMID 37024932, 2023). "The expression of JAK2 mRNA in tumor tissue in the control group was significantly increased." (PMID 38116545, 2023). "We further examined whether blocking JAK2 by AG490 could also inhibit the tumor-promoting effects on LSCC." (PMID 37062850, 2023). "In addition, the JAK2/STAT3 signaling pathway can regulate tumor angiogenesis through modulation of several angiogenesis-related genes." (PMID 36890596, 2023). "We hypothesize that intrinsic expression of CTLA-4, PDCD1 (PD1), CD274 (PD-L1), PDCD1LG2 (PD-L2), CD276 (B7-H3), JAK2, and FoXO1 in neoplastic cells depends on BC immunophenotype, stem cell properties, and tumor microenvironment." (PMID 36901916, 2023). "Thus, the reovirus contributed to JAK2 expression levels staying constant to a statistically significant level after D8, in contrast to its demonstrated downregulation in tumor cells." (PMID 37873786, 2023). "The overall expression of STAT3 and JAK2 in the tumor tissues was hardly affected." (PMID 38202610, 2023). "CAF in tumor microenvironment promotes GC progression through IL-6/JAK2/STAT3 signal transduction." (PMID 36591515, 2022).
tumor (continued). "It has been shown that VEGF causes an increase in MDSCs and suppresses anti-tumor immune responses because VEGF expression over-activates Janus Kinases 2/Signal Transducer and Activator of Transcription 3 (Jak2/STAT3) signaling, leading to aberrant myeloid differentiation in tumors." (PMID 36569915, 2022). "In addition, inhibition of IL-6 expression in CAFs or JAK2/STAT3 pathway in GC cells can impair the peritoneal metastasis of tumor induced by CAFs in vivo." (PMID 36591515, 2022). "Tumor conditioned medium could upregulate CXCL12 expression that facilitated the migration of human BM-MSCs to tumor sites by activating JAK2/STAT3 and MEK/ERK1/2 pathways." (PMID 36324128, 2022). "Thus, JAK2/STAT3 pathway is a well-known therapeutic target for curcumin inhibiting tumor initiation." (PMID 35883653, 2022). "Therefore, IL-6 enhances tumor cell proliferation, migration, and invasion via the JAK2/STAT3 signaling pathway." (PMID 36313702, 2022). "For example, in HPV infection individuals, PD-L1 expression is induced by EGFR and JAK2/signal transducer and activator of transcription 1 (STAT1)-dependent procedures; in particular, inhibition of JAK2 prevents re-regulation of PD-L1 in tumor cells, leading the increased immunologicity." (PMID 37305016, 2022). "To determine whether the kinase activity is required for tumor maintenance, we investigated the in vivo sensitivity of Pax5Jak2/+ B‐ALLs to JAK2 inhibition." (PMID 35156727, 2022). "The JAK2/STAT3 and PI3K/Akt pathways may play a major role in cancer angiogenesis, especially the latter, which is also implicated in tumor metastasis and invasion." (PMID 35984196, 2022). "In this study, we first reported that liensinine could suppress the activation of the JAK2/STAT3 pathway in tumor cells." (PMID 35116094, 2022). "These suggest that CAF in tumor microenvironment promotes the progress of GC through IL-6/JAK2/STAT3 signal transduction, and IL-6 targeted therapy may become a complementary treatment for GC by acting on stromal fibroblasts." (PMID 36591515, 2022). "Further, we found that the expression of BCL-2 downstream of JAK2/STAT3 was also reduced, and BCL-2 was associated not only with apoptosis but also with the infiltration of immune cells in the immune microenvironment of the tumor." (PMID 36582521, 2022). "Lastly, the use of VSV-GP, a potent oncolytic virus pseudotyped with the lymphocytic choriomeningitis virus (LCMV) envelope glycoprotein, together with the Jak1 and Jak2 inhibitor Ruxolitinib, led to transient tumour remission in mice following IP administration." (PMID 35805007, 2022). "In previous clinical trials, JAK inhibitors did not effectively inhibit tumor growth—especially when JAK2 mutations constitutively activated downstream signaling." (PMID 35269562, 2022). "In particular, the IL-6/STAT3 pathway was found to be preferentially active in CD44+CD24− breast cancer cells, which have stem-cell-like characteristics, compared with other tumor cell types, and the inhibition of JAK2 decreased their number and blocked the growth of xenografts." (PMID 36010693, 2022). "Furthermore, JAK2/STAT3 signaling pathway also serve as a crucial mediator for the anti-tumor effects of Scoparone, β-citric acid and Atractylenolide II." (PMID 35818076, 2022). "Through Western blot analysis of tumor tissues, we found that liensinine treatment significantly downregulated the expressions of p-STAT3 and p-JAK2, thereby causing a significant reduction in the ratio of p-STAT3/STAT3 and p-JAK2/JAK2." (PMID 35116094, 2022). "A deficiency in DENR leads to decreased JAK2 translation and impairs JAK-STAT signaling, thus reducing PD-L1 expression in tumor cells and repressing tumor growth by enhancing the anti-tumor killing activity of CD8+ T cells in the tumor microenvironments." (PMID 35440133, 2022).
tumor (continued). "The finding that the JAK2/STAT3 pathway could be blocked by excessive ROS was consistent with the tumor-related reports, but contrary to the conclusions of some inflammation-related studies." (PMID 35116094, 2022). "Therefore, mutations and deletions of proteins associated with this pathway on tumor cells, such as JAK1 and JAK2, STAT1, IRF1, and other IFN receptor chains, can lead to drug resistance to immunocheckpoint inhibitors." (PMID 36185620, 2022). "AKR1C1 is also a key component for the phosphorylation of STAT3 and it could facilitate the interaction of STAT3 with its upstream kinase JAK2, which promotes tumor metastasis in NSCLC." (PMID 35370661, 2022). "Furthermore, PTEN-null senescent tumors released immunosuppressive cytokines with the activation of the Jak2/Stat3 pathway and consequently decreased the immune response in the tumor microenvironment." (PMID 35267553, 2022). "From the analysis of cellular protein and tumor tissue protein by Western Blot and immunohistochemistry, it could be illustrated that Rh4 dramatically inhibited the expression of JAK2, STAT3 and p-STAT3, blocking the EMT procedure in LAC cells." (PMID 35216134, 2022). "Moreover, it also provided evidence that the downregulation of JAK2/NF-κB pathways was involved in the anti-tumor effect of polarized macrophages." (PMID 34034714, 2021). "Erianin, a natural product isolated from Dendrobium chrysotoxum Lindl, downregulates the IDO-induced tumor cells angiogenesis and endothelial cell-dependent angiogenesis by targeting the JAK2/STAT3 pathway and its downstream genes, such as matrix metalloproteinases-2 and -9." (PMID 34201791, 2021). "When analyzing genetic pathways for the five patients with both primary and recurrent tumor pathology, two of the most significantly altered pathways included cardiac β‐adrenergic signaling (Z score = −0.378; p = 0.0455) and the role of JAK2 in hormone‐like cytokine signaling (p = 0.0496)." (PMID 34729947, 2021). "Additionally, Ibrutinib-resistant primary CLL cell growth was inhibited by Cerdulatinib, and these anti-tumor effects were proposed to be linked to inhibition of BCR, IL-4/Jak1/Jak3/Stat6 and IL-6/Jak1/Jak2/Stat3 signaling." (PMID 34680353, 2021). "Moreover, the levels of PD-L1 in the CT26 tumor tissues were determined by western blotting after Foretinib treatment, which demonstrated that PD-L1, p-JAK2 and p-STAT1 (included S727 and Y701) were significantly increased, which was similar to the MC38 tumor." (PMID 34307367, 2021). "In order to show the relationship between Jak2 signaling and tumor progression." (PMID 34199353, 2021). "Alteration of IL7 signalling was common in iAMP21 tumours suggesting that JAK2 inhibitors may have utility in this group." (PMID 34753926, 2021). "Likewise, the use of pharmacologic JAK2 inhibition in addition to chemotherapy was shown to produce tumor growth inhibition in vivo." (PMID 33802575, 2021). "Moreover, Pacritinib was shown to be orally available in mouse models with high efficacy in suppressing Jak2-Stat5 signaling in a subcutaneous human xenograft tumor model." (PMID 34680353, 2021). "Although JAK2 mutant tumor cells can produce interferon (IFN)-γ, the JAK2–signal transducer and activator of transcription _(STAT) signal pathway cannot be activated by IFN-γ and cannot upregulate the expression of PD-L1, which leads to the weak killing effect of IFN on JAK2 mutant tumor cells." (PMID 34532293, 2021). "Interestingly, in vitro treatment with a combination of chemotherapy and momelotinib is a potent inhibitor of Jak2; it suppressed CSCs-like cells and reduced tumor burden in a mouse model of human ovarian cancer." (PMID 34199353, 2021). "In conclusion, our research demonstrated that GM-CSF potentially triggered the loss of tumor immune surveillance in ENKTL patients and promoted disease progression, which was associated with STAT5A mutations and JAK2 hyperphosphorylation, and then upregulates the expression of PD-L1." (PMID 34051805, 2021).
tumor (continued). "Recent evidence suggests that SOCS6 can inactivate the JAK2/STAT3 pathway in tumor cells." (PMID 33937336, 2021). "With the deepening of research, further understanding of ginkgolic acid inhibition of lncRNA MALAT1/JAK2 axis on the biological function of OCa cells and its role in the process of tumor development will be more conducive to the diagnosis, treatment, and prognosis assessment of OCa." (PMID 34987594, 2021). "Taken together, it is plausible to speculate that nifuroxazide treatment decreases tumor angiogenesis via the inhibition of the IL-6/Jak2/STAT3 pathway." (PMID 34833950, 2021). "Studies had shown that KIF20A might promote the proliferation, invasion and migration of tumor cells by activating the JAK2/STAT3 pathway." (PMID 33836688, 2021). "Hence, according to molecular signaling, nobiletin inhibits tumor progression by inhibiting the EGFR/JAK2/STAT3 pathway and PD-L1 expression in NSCLC cells." (PMID 34576006, 2021). "These mutations may be acquired early (patient #20, JAK2) or late during tumor development (patient # 24, JAK2)." (PMID 34581268, 2021). "Upregulation of JAK2 expression could enhance the proliferation, metastasis, and invasion characteristics of tumor cells, while downregulation of JAK2 expression has the opposite effect." (PMID 35047409, 2021). "In tumor tissues, four protective genes (JAK2, IL2RG, EEF1E1, and UBB) showed relatively low expression in the high‐risk group; in contrast, the expression of four risk genes (EPS8, FOXO1, STAT5A, and PAPPA) was more highly in the high‐risk group than that in the low‐risk group." (PMID 34825509, 2021). "This study exhibited that JaK2 was increased in resistant tissues and cells, and JaK2 upregulation could reverse the repression action of miR-377-3p on tumor progression and CDDP resistance in vitro." (PMID 34307356, 2021). "Overall, these findings indicate that consistent overexpression of the ALKBH5-HOXA10 loop in EOC could promote tumor growth and chemoresistance by mediating the JAK2/STAT3 signaling pathway." (PMID 34496932, 2021). "However, to our knowledge only the canonical JAK2/STAT3 pathway has been implicated in OCSC function, including tumor initiation and chemoresistance." (PMID 34645505, 2021). "In addition, inhibiting miR-216a-5p and activating the JAK2/STAT3 pathway can promote tumor cell spheroidization, up-regulating the levels of stem marker proteins CD90 and CD133." (PMID 34900727, 2021). "Compared with normal tissues, the expression of JAK2 in OC is downregulated, which may be related to the heterogeneity of the tumor." (PMID 34825509, 2021). "Blockade of IL-6 or JAK2 inhibited high-fat-diet-stimulated tumor progression." (PMID 33430277, 2021). "In addition, the JAK2/STAT3 pathway is involved in the SDF-1/CXCR4 interaction promoting mesenchymal stem cell migration in response to the tumor microenvironment." (PMID 34124069, 2021). "WB and IHC were employed to verify the SOCS3/JAK2/STAT3 expression in the tumor tissues of mice." (PMID 34388111, 2021). "Additionally, tumor formation in nude mice also demonstrated that ginkgolic acid inhibits tumor formation in nude mice by downregulating the lncRNA MALAT1/JAK2 axis." (PMID 34987594, 2021). "The secretion of Il-6 and Il-8 by GC-derived mesenchymal stromal cells and further activation of the JAK2/STAT3 pathway induces the polarization of macrophages into pro-tumor M2 phenotype, which consequently promotes GC metastasis via advancing the EMT process." (PMID 32268527, 2020). "Collectively, NaB could reduce tumor burden and inhibit JAK2/STAT3 signaling axis activation in mouse xenograft tumor models." (PMID 32518521, 2020). "Other mechanisms of PD-L1 upregulation are overexpression of Myc along with mutated KRAS; activating mutations of EGFR, KRAS or JAK2; and CMTM4 and CMTM6 posttranslational regulation in tumor cells and DCs, in addition to other posttranscriptional modifications." (PMID 33322522, 2020).
tumor (continued). "Based on past experiments, JAK-2 acts as a downstream target of miR-375 and is regulated by miR-375, which affects the normal expression of genes and proteins in the signal transduction pathway and affects the proliferation and invasion of tumor cells." (PMID 32382558, 2020). "The JAK2/STAT3 signaling pathway has been widely studied in different steps of tumor development and may act as a promising molecular therapeutic target." (PMID 32358527, 2020). "Thereby, we hypothesize JAK2 to interact with the tumor microenvironment leading to re-activation of macrophage effector function." (PMID 32824276, 2020). "Mechanistically, IL4Rα and IL13Rα1 could increase JAK2 signaling pathway and suppress tumor-suppressive activity of FOXO3." (PMID 31540495, 2019). "Moreover, high lincRNA-p21 expression exerted tumor suppressor activity by inhibiting JAK2/STAT3 signaling activation, which suggest that lincRNA-p21 was deeply involved in aggressive progression in HNSCC." (PMID 30857539, 2019). "As JAK2 activation could lead to PD-L1 expression resulting in T-cell anergy and immune escape, ruxolitinib could inhibit this T-cell exhaustion in tumor microenvironment." (PMID 31707975, 2019). "First, the influence of JAK2 signaling on the growth of tumor cells in human might be different from in vitro and in vivo models, and this might be related with different outcome of ruxolitinib in HL and PMBCL of this pilot study." (PMID 31707975, 2019). "Aberrant JAK/STAT signaling has been identified as a strong oncogenic factor involved in tumor growth, invasion, and metastasis; thus, potent JAK2 and STAT3 inhibitors have been developed and are currently in different stages of preclinical and clinical investigations." (PMID 31511084, 2019). "This expression was dependent on activation of either NF-κB, JAK1/JAK2 or BTK pathways since these pathways were activated in tumor B-cells and ex vivo treatment with the inhibitory molecules PHA-408, ruxolitinib and ibrutinib led to decrease of its expression." (PMID 31382969, 2019). "Herein, we demonstrated for the first time that macrophages play an essential role in the potent pro-tumor effect of GC-MSCs; in turn, GC-MSCs induce the polarization of macrophages into the M2 subtype through secreting IL-6 and IL-8 via the JAK2/STAT3 signaling pathway." (PMID 31801938, 2019). "Additionally, the apoptotic cell number within the primary tumor was increased by RT alone, and more importantly, apoptotic rates were further significantly enhanced by JAK2 silencing in combination with RT." (PMID 31511084, 2019). "Indeed, JAK1 and JAK2 were activated/phosphorylated in tumor cells of lung AC patients as determined by a pathologist (H.P.)." (PMID 31407334, 2019). "Accumulating data demonstrates that SHP-1 may be able to modulate stemness and the epithelial-to-mesenchymal transition (EMT) of tumor cells by targeting the JAK2/STAT3 signaling pathway." (PMID 31569687, 2019). "it has been reported that EPO could switch on tumor angiogenesis just by activating JAK2/STAT5 and PI3K/Akt signal pathways." (PMID 30915348, 2019). "Thus, increased levels of miRNAs induce downregulation of the JAK2 protein, thus promoting apoptosis and inhibiting proliferation of tumor cells by downregulating the anti-apoptotic protein, Bcl-xL." (PMID 30884772, 2019). "In addition to DNMT3A, mutations in genes such as JAK2 and TET2, which are also located in hematopoietic clones, can confound the detection of tumor‐derived variants in blood." (PMID 30672098, 2019). "We suggest that there are some other vital oncokinases, such as JAK2, that can regulate autophagy, and that they engage autophagy at one of the earliest steps of the entire process so as to affect tumor cells growth, proliferation, and chemotherapy resistance in tumors." (PMID 31378785, 2019). "IFNγ exerts anti-tumor function mainly through JAK2 signaling." (PMID 30948928, 2019).